GRIN2B (glutamate ionotropic receptor NMDA type subunit 2B)
Diseases named in the same sentence as GRIN2B in open-access papers (continued):
Sharing a sentence is not in itself a finding about the gene and the disease.
autism (39 papers, 2010 to 2025). Persistent deficits in social interaction and communication and interaction as well as a markedly restricted repertoire of activity and interest as well as repetitive patterns of behavior. "The GRIN2B gene, known for its involvement in encoding a glutamate receptor subunit crucial for neuron communication and associated with autism, was a focus of this study." (PMID 38562305, 2024). "We also observed decreased activity blocked by TTX and a decrease in the expression of NMDA receptor subunit GRIN2B, a gene previously associated with autism, in our FMR1 KO and FXS patient lines iPSC-derived neurons." (PMID 37834379, 2023). "While de novo rare mutations of GRIN2B have been identified in autism patients, common variants and rare inherited variants have not yet been systematically investigated." (PMID 25656819, 2015). "All evidence indicated that multiple common variants of GRIN2B and related haplotypes were associated with autism risk." (PMID 25656819, 2015). "To evaluate genetic variants of GRIN2B in autism etiology, we performed a system association study of common and rare variants of GRIN2B and autism in cohorts from a Chinese population, involving a total sample of 1,945 subjects." (PMID 25656819, 2015). "Our study for the first time reveals that common variants and related haplotypes of GRIN2B are associated with autism risk." (PMID 25656819, 2015). "In this study, we examined the association of common and rare variants of GRIN2B with autism risk in Han Chinese populations." (PMID 25656819, 2015). "This pattern was consistent with those of other autism risk genes, such as GRIN2B (correlation coefficient (r) = 0.65, p < 2.2e-16), SCN2A (r = 0.64, p < 2.2e-16), and CACNA1D (r = 0.51, p < 2.2e-16), suggesting a coordinated increase during the fetal third trimester." (PMID 39363111, 2024). "Variants of GRIN2B were associated with autism in a Chinese population, including variants coding for the ion selectivity region of the channel and the carboxy-terminal domain (CTD), the latter domain interacts with binding partners (e.g., CAMKII, PSD-95 and α-Actinin)." (PMID 35204682, 2022). "GRIN2B, an autism-risk gene, further suggests that pathways involved in early circuitry formation may be vulnerable targets in autism." (PMID 27909399, 2016). "To test whether rare variants of GRIN2B are associated with autism risk, we first performed burden analysis using Asian samples (CHB, CHS and JPT) from the 1000 genome project as controls." (PMID 25656819, 2015). "The anti-correlation of synapse-related gene changes between the thalamus and SSC also occurs strongly in the ASD-linked Grin2b+/− mutant, but in the opposite direction; in that context, we note that altered sensory processing is increasingly recognized as a characteristic feature of autism." (PMID 41022686, 2025). "For example, the variants might be involved in the risk of autism by regulating GRIN2B expression." (PMID 25656819, 2015). "Using a rat model induced by prenatal exposure to valproic acid, we examined the impact of HBOT on autism-like behaviors and GRIN2B gene expression." (PMID 38562305, 2024). "In mice, sevoflurane exposure induced autism-like behaviours and led to the downregulation of high-risk autism genes, including ARID1B, GABRA5, GABRB3, GRIN2B, SHANK3 and SUV420H1." (PMID 39372140, 2024). "Among known NMDAR subunit genes, GRIN2B is one of the most frequently mutated ASD-risk genes, belonging to category 1 in the Simons Foundation Autism Research Initiative (SFARI) gene list, and shows stronger impacts on ASD than mutations in GRIN1 or GRIN2A." (PMID 32353004, 2020). "Our findings imply that HBOT might have a potential role in ameliorating autism-related behaviors in the VPA rat model of autism through potential modulation of GRIN2B gene expression." (PMID 38562305, 2024). "However, contradictory reports exist, showing increased GRIN2B expression in autism, contrasting our results." (PMID 38562305, 2024).
autism (continued). "Thus, the present study aimed to investigate the effect of HBOT at pressures of 2 and 2.5 atmosphere absolute on autistic-like behaviors and GRIN2B gene expression in the VPA-induced rat model of autism." (PMID 38562305, 2024). "Based on some research, a decrease in the expression or function of the GRIN2B gene can impair NMDA-dependent signaling and can disrupt the excitatory-inhibitory balance of the middle area of the frontal lobe causing some autism-like behaviors such as social interaction disorders." (PMID 38562305, 2024). "Furthermore, fentanyl induced autism-like behaviors in both young male and female mice, downregulating Grin2b expression and GluN2B protein levels in the anterior cingulate cortex through hypermethylation of Grin2b." (PMID 39635461, 2024). "(S) Log-normalized counts of transcripts for the autism-related transcription factor Auts2 and several neurotransmitter receptor and ion channel genes whose expression changes across postnatal development (Glra1, Grin2b, Kcnj3, and Kcnq3)." (PMID 36876911, 2023). "Thus, variants of GRIN2B and NBEA confer risk to autism, supporting therapeutic strategies to modulate endogenous." (PMID 35204682, 2022). "Interestingly, our recent data demonstrate that Grin2b induction upon behavioral stimulation is impaired in Tbr1+/- mice, which thus show autism-like behaviors." (PMID 25309323, 2014). "Additionally, we noted massive albeit bidirectional hippocampal changes in the autism-related transcripts of Grin2b, PTEN and SHANK3, predicting behavioral differences; but not in the inflammation-associated CHRNA7, indicating limited relevance for brain inflammation." (PMID 32503154, 2020). "Importantly, all molecules changed in the striatal Shank3Δ11-/- mutant PSD that matched with the SFARI autism gene database were reduced and comprised the murine homologs of proteins encoded by several major ASD candidates including NCKAP1, GRIN2B and TRIO, 3 of the 65 high-risk ASD TADA genes." (PMID 28261056, 2017). "The six candidate genes sequenced, CNTN1, FOXJ2, GRIN2B, NAB2, NELL2 and SRGAP1, were selected based on their putative functions, and their relationships to genes potentially involved in the pathology of language impairments, auditory processing deficits, autism and dyslexia." (PMID 20345892, 2010).
Parkinson disease (24 papers, 2010 to 2024). A progressive degenerative disorder of the central nervous system characterized by loss of dopamine producing neurons in the substantia nigra and the presence of Lewy bodies in the substantia nigra and locus coeruleus. "Association of DRD3 and GRIN2B with impulse control and related behaviors in Parkinson's disease." (PMID 21034472, 2010).
autism spectrum disorder (22 papers, 2013 to 2025). A spectrum of developmental disorders that includes autism, and Asperger syndrome. "Three de novo GRIN2B (a nonsense, a slice, and a frameshift) variants were first described in 2012, associated with autism spectrum disorder." (PMID 39596051, 2024). "In a very recently published paper, the same group reported on de novo GRIN2B mutations in four out of 2446 probands with autism spectrum disorder, leading to the assumption that GRIN2B belongs to the recurrently mutated genes in ASD/ID phenotypes." (PMID 23718928, 2013). "In 2011, a single individual with a GRIN2B mutation was identified within a group of 20 individuals with autism spectrum disorders." (PMID 23718928, 2013). "Extensive evidence links Glutamate receptor, ionotropic, NMDA2B (GRIN2B), encoding the GluN2B/NR2B subunit of N-methyl-D-aspartate receptors (NMDARs), with various neurodevelopmental disorders, including autism spectrum disorders (ASDs), but the underlying mechanisms remain unclear." (PMID 32353004, 2020). "Mutations in GRIN2B, which encodes the GluN2B subunit of NMDA receptors, lead to autism spectrum disorders (ASD), but the pathophysiological mechanisms remain unclear." (PMID 34393725, 2021).
developmental delay (20 papers, 2014 to 2025). "We identified GRIN2B gain-of-function mutations as a cause of West syndrome withsevere developmental delay as well as of ID with childhood onset focal epilepsy." (PMID 24272827, 2014).
Epileptic encephalopathy (18 papers, 2014 to 2025). A condition in which epileptiform abnormalities are believed to contribute to the progressive disturbance in cerebral function. "For example, mutations in GRIN1 are associated with early infantile encephalopathy and developmental delay, while GRIN2A and GRIN2B mutations contribute to epilepsy syndromes like Landau–Kleffner syndrome and epileptic encephalopathy, respectively." (PMID 39596430, 2024). "Glutamate receptor ionotropic NMDA2B (Grin2b) is linked to epileptic encephalopathy, ASD, and other neurological disorders in which Grin2b haploinsufficiency is often an important factor." (PMID 36768153, 2023). "GRIN2B mutation is a rare cause of severe epileptic encephalopathy." (PMID 35069111, 2021). "Moreover, one GoF GRIN2B mutation was reported to cause West syndrome and epileptic encephalopathy." (PMID 38003469, 2023). "Moreover, a GoF GRIN2B mutation was reported to cause West syndrome and epileptic encephalopathy." (PMID 38003469, 2023). "Mutations in genes encoding NMDAR subunits, such as GRIN1, GRIN2A, GRIN2B, GRIN2C, and GRIN2D, have been linked to various epileptic phenotypes, ranging from focal and generalized seizures to severe epileptic encephalopathies." (PMID 39596430, 2024). "Grin2a and Grin2b encodes subunits of the glutamate ionotropic receptor NMDA and their mutations are related to idiopathic focal epilepsy and epileptic encephalopathy, respectively." (PMID 34177758, 2021). "Confirmation that our prioritization approach works came with two recent publications reporting GNAO1 and GRIN2B as a true Epileptic Encephalopathy genes." (PMID 25014031, 2014). "GRIN2B is a NMDA receptor subunit associated with developmental and epileptic encephalopathy." (PMID 36361815, 2022). "Similarly, novel pharmacological agents such as NMDA receptor antagonists for GRIN2A/GRIN2B mutations, KCNQ channel openers for KCNQ2-related epileptic encephalopathies, and IGF-1 analogues for trophic deficiency syndromes signify the forthcoming generation of personalized treatments." (PMID 41470225, 2025). "Of the nineteen genes that we predicted with the highest likelihood to be true Epileptic Encephalopathy genes, two (GNAO1 and GRIN2B) have recently been independently reported and confirmed." (PMID 25014031, 2014).
Dyskinesia (15 papers, 2012 to 2024). A movement disorder which consists of effects including diminished voluntary movements and the presence of involuntary movements. "We have in the past studied the relationship between GRIN2A and GRIN2B variants and the occurrence of drug-induced dyskinesia." (PMID 34685369, 2021). "Our results indicate that GRIN2B variations play a pivotal role in the rigidity or dyskinesia symptoms of PD." (PMID 39758784, 2024). "It was partly explained by a de novo likely pathogenic variant in the GRIN2B gene (NM_000834.5:c.1246T>C; p.Phe416Leu) which causes a dominant neurodevelopmental disorder (OMIM #616139) with described abnormal movement disorders such as dystonia or dyskinesia." (PMID 35886058, 2022).
Huntington disease (15 papers, 2011 to 2025). Huntington disease (HD) is a rare neurodegenerative disorder of the central nervous system characterized by unwanted choreatic movements, behavioral and psychiatric disturbances and dementia. "The aim of this study was to replicate association of variations in the N-methyl D-aspartate receptor subtype genes GRIN2A and GRIN2B in the “REGISTRY” cohort from the European Huntington Disease Network (EHDN)." (PMID 21989477, 2011). "We also found many differentially expressed genes related to the Huntington disease (HD) pathway in both areas of the MPS II mouse model; among these, Bbc3, Bdnf, Crebbp, Dctn1, Dlg4, Gpx1, Grin1, Grin2b, Itpr1, and Pparg are up-regulated, while Dnaic2, Dnali1, Hap1, and Vdac2 are down-regulated." (PMID 28513549, 2017).
cognitive decline (12 papers, 2012 to 2025). "In a separate cohort study, cognitive decline in boys with prenatal bisphenol F exposure was linked to hypermethylation of the CpG3 locus in the regulatory region of the GRIN2B gene." (PMID 40438331, 2025). "Knowing a functional polymorphism that increases levels of GRIN2B mRNA and possibly the number of GluN2B subunits suggests a way for protecting the brain from age-related cognitive decline." (PMID 28439047, 2017). "Genetic enhancement of Grin2b expression increases NMDA receptor-dependent synaptic plasticity and associated learning and memory functions, and hippocampal reductions in Grin2a and Grin2b have been observed in the AD brain, correlating with cognitive decline." (PMID 26221964, 2015). "To further ascertain the impact of the GRIN2B rs219882 genotype on cognitive decline, we employed a linear mixed-effects model to examine the rate of change in the MoCA scores and its seven subscale scores, adjusting for age, sex, and years of formal education at baseline." (PMID 39758784, 2024).
West syndrome (12 papers, 2013 to 2025). "Multiple mutations of Grin2b, the gene that encodes GluN2B, were identified in patients with infantile spasms, and Grin2b is also classified as the causative gene for DEE-27." (PMID 35887274, 2022). "We revealed de novo mutations in GRIN2B encoding the NR2B subunit of theN-methyl-D-aspartate (NMDA) receptor in 2 individuals with West syndrome and severe developmentaldelay as well as 1 individual with ID and focal epilepsy." (PMID 24272827, 2014). "In summary, we postulate that genetic alterations in GRIN2B are responsible for∼2% (2 of 91) of EE cases, preferentially causing IS and West syndrome." (PMID 24272827, 2014).
bipolar disorder (9 papers, 2013 to 2025). A disorder of the brain that causes unusual shifts in mood, energy, activity levels and the ability to carry out day-to-day tasks. "Furthermore, genetic association studies in the Chinese Han population have identified a significant positive correlation between specific single nucleotide polymorphisms (SNPs) in the GRIN2B gene and bipolar disorder." (PMID 40438331, 2025). "We identified aberrant methylation levels at multiple CpG sites within the GRIN2B gene promoter region in patients with bipolar depression compared to healthy controls." (PMID 40438331, 2025). "In our research, we identified differential sites in the promoter region of the GRIN2B gene, including CpG1, CpG3, CpG5, CpG7, CpG9, CpG10, and CpG12, with varying DNA methylation levels between patients with bipolar depression and healthy controls." (PMID 40438331, 2025). "Subsequently, we analyzed the correlation between GRIN2B gene promoter methylation levels and cognitive performance in patients with bipolar depression." (PMID 40438331, 2025). "In this study, we measured the methylation levels of the promoter region of the GRIN2B gene in peripheral blood samples from patients with bipolar depression and healthy controls using the MassARRAY method." (PMID 40438331, 2025). "The consistency of our findings with those from a larger, well-powered study underscores the robustness of our conclusions and supports the potential role of GRIN2B methylation as an independent biomarker in bipolar disorder." (PMID 40438331, 2025). "To test this hypothesis, we compared the cognitive functions of patients with bipolar depression and healthy controls while measuring DNA methylation levels in the promoter region of the GRIN2B gene in peripheral blood." (PMID 40438331, 2025). "In this study, we observed that elevated methylation levels at most sites in the promoter region of the GRIN2B gene, such as CpG1, CpG7, CpG11, and CpG12, were positively correlated with cognitive function in patients with bipolar depression, while an inverse trend was observed at the CpG8 locus." (PMID 40438331, 2025). "Given this context, we hypothesize that changes in DNA methylation levels in the promoter region of the GRIN2B gene in patients with bipolar depression may lead to reduced expression of NMDAR receptor subunits and glutamatergic dysfunction, thereby affecting cognitive function." (PMID 40438331, 2025). "Recent studies have demonstrated that patients with bipolar disorder exhibit reduced NMDAR activity in key brain regions, such as the dorsolateral prefrontal cortex, anterior cingulate gyrus, and hippocampus, suggesting that the GRIN2B gene may play a pivotal role in the pathophysiology of BD." (PMID 40438331, 2025).
Encephalopathy (9 papers, 2012 to 2025). Encephalopathy is a term that means brain disease, damage, or malfunction. "L‐serine, a precursor of the NMDAR co‐agonist, D‐serine, has been trialed in children with encephalopathy associated with LOF GRIN2A/GRIN2B mutations, and reported to improve seizure frequency, behavior, and neuro‐cognitive skills." (PMID 40944498, 2025). "A previous study of 58 individuals with GRIN2B encephalopathy revealed that 52% (30/58) of the patients have had seizures with a variable age of onset (0–9 years)." (PMID 34858471, 2021). "Whereas, another study showed that no seizure reduction was found in patients with GRIN2B mutation-related encephalopathy treated by memantine despite improved consciousness, behavior, and sleep." (PMID 35069111, 2021).
gastric cancer (9 papers, 2014 to 2023). A primary or metastatic malignant neoplasm involving the stomach. "Furthermore, GRIN2B and GRIN2A genes have been found to be highly methylated in various carcinomas: GRIN2B in esophageal, head, and neck squamous carcinomas, gastric cancer, and lung adenocarcinomas; and GRIN2A in colorectal cancer tissues." (PMID 36768862, 2023). "However, it has been reported that active GRIN2B has an important influence on the survival of breast cancer patients and that GRIN2B methylation is a common and important biologically relevant event in gastric cancer progression." (PMID 29785036, 2018). "Conversely, the levels of the tumor suppressors (e.g., DAPK1, TIMP3, GRIN2B, SLC5A8, and CDH1) are low in the gastric tissues of patients with gastric cancer." (PMID 35211104, 2022).
attention deficit-hyperactivity disorder (8 papers, 2013 to 2025). A disorder characterized by a marked pattern of inattention and/or hyperactivity-impulsivity that is inconsistent with developmental level and clearly interferes with functioning in at least two settings (e.g. at home and at school). "Numerous studies have reported an association between GRIN2B variants and attention-deficit/hyperactivity disorders (ADHD)." (PMID 41303266, 2025). "Grin2b is a particularly interesting target as genetic polymorphisms in this gene have been consistently found to be associated with neurodevelopmental diseases/disorders, such as Attention Deficit Hyperactivity Disorder (ADHD), Autism Spectrum Disorder (ASD), and schizophrenia." (PMID 30054528, 2018).
breast carcinoma (8 papers, 2014 to 2023). "GRIN2B is involved in breast cancer progression and acts as a promoter of CpG islands." (PMID 36338974, 2022).